IL6 (interleukin 6)
Diseases named in the same sentence as IL6 in open-access papers (continued):
Sharing a sentence is not in itself a finding about the gene and the disease.
pulmonary fibrosis (continued). "Elevated CRP is a well-established marker of systemic inflammation and is involved in the pathogenesis of pulmonary fibrosis by promoting alveolar epithelial injury and fibroblast activation through interleukin-6 (IL-6) and transforming growth factor-beta (TGF-β) signaling pathways." (PMID 41277954, 2025). "Furthermore, we found a strong positive correlation between ICAM1 + EVs and well-known mediators of SSc lung fibrosis (IL6 and VEGF) within both ILD and PF-ILD subgroups." (PMID 40370719, 2025). "Moreover, the elevated levels of IL-6 were observed in the lung tissues and serum of pulmonary fibrosis patients." (PMID 40182855, 2025). "These recruited MCs are activated via TGF-β priming and release of IL-6 as seen in lung fibrosis." (PMID 39195287, 2024). "Additionally, the BALF concentrations of TNFα, interleukin-6 (IL-6), osteopontin, interferon-γ (IFNγ), and SP-D were substantially lower in TG mice with lung fibrosis than in their WT counterparts." (PMID 39329706, 2024). "High IL-6 levels exert marked effects on other inflammatory factors, immune cells, and oxidative stress, which are closely related to the pathogenesis of silica-induced pulmonary fibrosis." (PMID 38515835, 2024). "In this study, we verified that diazepam can effectively inhibit inflammation in pulmonary fibrosis; specifically, diazepam can effectively inhibit the expression of the inflammatory cytokines IL-4, IL-6 and TNF-α and effectively alleviate the occurrence of pulmonary fibrosis." (PMID 38875245, 2024). "Also, FPNI treatment prevented the upregulation of senescence markers that are well-known to be associated to lung fibrosis, such as TNF-α, Il6, Cdkn1a and Cdkn1b along with that of collagen isoforms Col1a1 and Col3a1." (PMID 38167804, 2024). "Obese Nod2−/− mice had higher inflammatory cell infiltration in the bronchial alveolar lavage (BAL) and lungs, pulmonary fibrosis, mucus levels, hypertrophy and hyperplasia of goblet cells, M2 alveolar macrophage infiltration, interleukin-4 (IL-4), IL-5, IL-6, and lower CXCL1 and IL-22." (PMID 39507249, 2024). "Iloprost prevents pulmonary fibrosis, possibly by upregulating anti-fibrotic mediators (interferon γ and C-X-C motif chemokine ligand 10) and downregulating pro-inflammatory and pro-fibrotic cytokines (tumor necrosis factor α, IL-6, and TGF-β1)." (PMID 38878214, 2024). "Furthermore, blockade of the IL-6 signal during the chronic stages of lung injury benefits lung fibrosis." (PMID 39596365, 2024). "Moreover, naringenin was shown to have a significant therapeutic effect on Mycoplasma pneumoniae-induced lung injury in mice by inhibiting pulmonary fibrosis and inhibiting the secretion of inflammatory cytokines such as IL-6, IL-1β, TNF-α, and TGF-β." (PMID 38074219, 2023). "Moreover, in idiopathic pulmonary fibrosis, uPA exerts a strong pro-fibrotic effect that involves uPA-dependent IL-6 upregulation." (PMID 36674896, 2023). "Notably, combined immunotherapy with CD47- and IL-6-blocking agents has been shown to reverse fibrotic conditions in mice, suggesting new therapeutic alternatives for treating pulmonary fibrosis." (PMID 36842152, 2023). "acute lung injury score, fibrosis score in mice with BLM-induced pulmonary fibrosis were increased, and the inflammatory markers such as IL-6, TNF-α and monocyte chemoattractant protein-1 in bronchoalveolar lavage fluid were also increased, while the anti-inflammatory cytokine IL-10 was decreased." (PMID 38007420, 2023). "Moreover, it has been previously demonstrated that the high level of uPA exerts a prominent pro-fibrogenic effect in idiopathic pulmonary fibrosis that involves uPA-dependent IL-6 upregulation." (PMID 36674896, 2023). "Furthermore, we confirmed that the worsened pulmonary fibrosis in Plaur-/- mice was accompanied by IL-6 upregulation, which was in agreement with the previously established link between uPA and IL-6 in lung fibrosis." (PMID 36674896, 2023).
pulmonary fibrosis (continued). "Elevated levels of IL-6 and IL-17 have been related to pulmonary fibrosis, and the elements of the IL-17A signaling cascade may serve as possible treatment targets for the treatment of fibroproliferative lung disorders." (PMID 37858084, 2023). "In the early stage of the development of alveolar inflammation to pulmonary fibrosis, pro-inflammatory cytokines such as TNF-α, IL-1 and IL-6 increase, which play an important pathogenic role, and inflammatory cells also induce the production of matrix metalloproteinases." (PMID 37809072, 2023). "IL-6 gene knockout mice showed attenuated irradiation or bleomycin-induced pulmonary fibrosis." (PMID 37773193, 2023). "Spn infection may also cause the depletion of Regulatory T cells by upregulating the response of Th1/2 cytokines (TNF-α, IL-6), leading to the deterioration of lung fibrosis in mice overexpressing TGF-β1." (PMID 38007420, 2023). "In HFD related obesity, adipocytes and macrophages in the adipose tissue generated pro-inflammatory cytokines such as TNFα and IL-6 which could provoke systemic inflammation and contribute to the progression of lung fibrosis." (PMID 36979493, 2023). "In retrospective studies from China, higher levels of serum lactic dehydrogenase and inflammatory biomarkers, including C-reactive protein (CRP), and interleukin-6 (IL-6) were found in the subgroups of patients who presented changes compatible with pulmonary fibrosis on follow-up CT scans." (PMID 37371834, 2023). "HSP90 may also contribute to the development of pulmonary fibrosis through IL-6, as HSP90 mediates activation of the nuclear factor kappa light chain enhancer in the B cell (NF-κB) dependent inflammatory pathway, promoting IL-6 production." (PMID 37089962, 2023). "In addition, Longidaze inhibited the inflammatory response in pulmonary fibrosis, and decreased the levels of IL-6, TNF-α, and hyaluronic acid in lung tissue and the recruitment of inflammatory cells into lung tissue." (PMID 37763335, 2023). "In addition, IL-6 is elevated in murine models of silica- and bleomycin-induced pulmonary fibrosis and in humans with pulmonary fibrosis." (PMID 37887075, 2023). "It was found that the affinity was similar to the docking scores of IL6 and TNFα, indicating that these key active components may play a key role in the treatment of pulmonary fibrosis." (PMID 35370663, 2022). "These proteins that cause respiratory distress and that are the targets of kinase inhibitors include those that contribute to the cytokine release syndrome (cytokines–IL-6 and TNF-α) and proteins associated with inflammation and the induction of pulmonary fibrosis (pro-inflammatory cytokine TGF-β)." (PMID 35444538, 2022). "Type II alveolar epithelial cell injury can be reduced by inhibiting the STAT3 pathway 47, indicating that IL-6 may participate in pulmonary fibrosis through alveolar epithelial cells." (PMID 36147459, 2022). "Our data also revealed a significant increase in IL6 expression that was reduced in IKBM mice which may correlate an association between BMPR1A-IL6 and NF-κB in pulmonary fibrosis." (PMID 35083615, 2022). "GSPE inhibited the BLM-induced IL-6 for early lung fibrosis and TGF-β for late lung fibrosis." (PMID 35355866, 2022). "In addition, IL-1β also stimulates the release of IL-6, which not only play the pro-inflammatory role, but also aggravates the pulmonary fibrosis by activating STAT3 pathway." (PMID 36733806, 2022). "Moreover, immunization of mice with TOPO-I and Freud adjuvant induced ATA antibody generation, IL-6 production, and skin and lung fibrosis." (PMID 35837382, 2022). "ADAM17 is involved in a variety of inflammatory processes, including activation and release of TNF, modulation of neuregulins such as AREG, and being a necessary cofactor for IL6 trans-signaling, which has been shown to promote pulmonary fibrosis in bleomycin injury." (PMID 36291184, 2022).
pulmonary fibrosis (continued). "Thus, while blockade of IL-6 signaling attenuates pulmonary fibrosis, IL-6 protects against oxidant-induced death of alveolar epithelial cells, and it regulates surfactant homeostasis in ATII cells." (PMID 35977489, 2022). "SARS-CoV-2 virus binds to angiotensin converting enzyme 2 (ACE2) and alters renin-angiotensin system activities, thus leading to enhanced inflammation (increased levels of VEGF, IP-10/CXCL10, MCP-3/CCL7, IL-6, IL-1, ROS etc.)and development of pulmonary fibrosis." (PMID 35139898, 2022). "Thus, it is reasonable that increased IL6 secretion caused Tregs to differentiate into Th17 subsets, thereby increasing IL17 and TGF-β expression levels and ultimately promoting pulmonary fibrosis." (PMID 36544757, 2022). "Other data obtained after analyzing a cohort of 68 SS patients support the prognostic value of IL-6, with increased values being correlated with the extension of skin involvement at the 3-year follow-up, the development of pulmonary fibrosis, and worse long-term survival." (PMID 35203527, 2022). "IL-6 is enhanced in mice and humans with pulmonary fibrosis." (PMID 35355866, 2022). "IL-6 has also been proposed to cause lung fibrosis, it skews the inflammation towards Th17 type and also results in suppression of Th1 response and differentiation of CD4+ cells into a profibrotic Th2 type which promotes lung fibrosis." (PMID 36106257, 2022). "Pulmonary fibrosis has many inductors, starting from the endothelial lesions initiated by the viral aggression, followed by the release of fibrosis-inducing factors such as IL-6, transforming growth factor β (TGF-β), plasminogen activator inhibitor-1 (PAI-1)." (PMID 36010377, 2022). "Here, we investigated whether KO mice had any deviation in cytokine expression and found out that the expression of the proinflammatory cytokine IL-6 was at least half of that in WT mice after an induced lung fibrosis with bleomycin." (PMID 34451852, 2021). "Suppression or deletion of IL-6 suppresses M2 macrophage polarization and attenuates lung fibrosis." (PMID 34719405, 2021). "In other words, higher biomechanical stress upon breathing due to a higher deposition of ECM proteins could explain the higher expression of IL-6 in WT mice with lung fibrosis compared with the KO mice." (PMID 34451852, 2021). "Similarly, genes associated with ECM production and remodeling were significantly decreased with the loss of IL-31RA; these genes included MMP13 and TIMP1, as well as IL-6 which increased in wildtype mice during bleomycin-induced pulmonary fibrosis." (PMID 33815402, 2021). "Involved mediators in lung fibrosis, such as interleukin 6 (IL-6), vascular endothelial growth factor (VEGF) and hepatocyte growth factor (HGF), are produced by fibroblasts and may induce both pro- and antifibrotic events in the alveolar regions." (PMID 33419174, 2021). "Accelerated lung fibrosis in some COVID-19 patients after the resolution of infection may be triggered by elevated levels of pro-inflammatory cytokines, in particular IL-6 and TGF-β, which are implicated in the pathogenesis of lung fibrosis." (PMID 34276671, 2021). "Indeed, stimulation of airway epithelial cells with IL-31 induced an increased production of MCP1 and IL-6 cytokines known to play a role in the development of pulmonary fibrosis." (PMID 33815402, 2021). "A similar approach has been fruitful in SSc for serum IL6 and lung function decline, in idiopathic pulmonary fibrosis with serum MCP1 predicting respiratory outcome, and in SSc-associated pulmonary arterial hypertension (PAH), where MCP1 showed relevant changes after treatment." (PMID 33604504, 2021). "IL-6 has been shown to promote pulmonary fibrosis through the STAT pathway, so IL-6 may be one of the important factors for SARS-CoV-2-induced pulmonary fibrosis." (PMID 34876129, 2021).
pulmonary fibrosis (continued). "Although blocking antibodies against CD47 and IL-6 are relatively safe, clinical experience with PD-L1 inhibitors in cancer demonstrate severe pulmonary side effects potentially limiting their use and warranting caution in pulmonary fibrosis patients." (PMID 32493933, 2020). "Likewise, Thalidomide was able to reduce macrophages, and lymphocytes count in bleomycin (BLM)-induced pulmonary fibrosis mice model and to suppress IL-6, IL-8, TNF-α, and TGF-β levels in their bronchoalveolar lavage fluid (BALF)." (PMID 32574274, 2020). "IL-6 may result in increased alveolar-capillary blood-gas exchange dysfunction, especially impaired oxygen diffusion, and lead to pulmonary fibrosis and organ failure." (PMID 33075088, 2020). "Moreover, studies have shown that paraquat can activate inflammatory related factors including TNFα, NF-κB, interleukin 1β, and IL-6, which in turn contribute to the development of pulmonary fibrosis." (PMID 33123215, 2020). "Here, we show that transglutaminase 2 (TG2), previously reported to elicit a TH17 response by increasing IL-6 expression in a mouse model of lung fibrosis, mediates the upregulation of cytokines and chemokines by activating NF-κB in imiquimod (IMQ)-treated keratinocytes." (PMID 32355189, 2020). "Similarly, B6.129S2-Il6tm1Kopf/J (IL-6 knockout) mice treated with anti-CD47 antibody and the PD-1 blocking reagent HAC similarly resolved their lung fibrosis confirming synergistic antifibrotic efficacy of IL-6 and immune-checkpoint inhibition." (PMID 32493933, 2020). "In addition, we detected increased IL-6 and family members in our Jun-induced pulmonary fibrosis mouse lung washings." (PMID 32493933, 2020). "Moreover, the STAT3 inhibitor S31-201 reversed miR-301a expression in fibroblasts induced by TGF-β and IL-6, thus implying that the activation of miR-301a in pulmonary fibrosis depended on STAT3." (PMID 32585629, 2020). "Furthermore, a recent study in the bleomycin-induced scleroderma mouse model demonstrated that inhibition of BAFF attenuates skin and lung fibrosis with reduction of IL-6–producing effector B cells." (PMID 33105647, 2020). "The results of the present investigation are in accordance with previous findings where instillation of BLM caused ROS influx which in turn phosphorylated IκBα and activated NF-κB resulting in the release of pro-inflammatory cytokines (TNF-α, IL-1β, and IL-6) and brought out pulmonary fibrosis." (PMID 31611754, 2019). "Hesperidin alleviates BLM-induced IPF via inhibition of TGF-β1/Smad3/AMPK and IκBα/NF-κB pathways which in turn ameliorate the modulation of oxido-inflammatory markers (Nrf2 and HO-1) and pro-inflammatory markers (TNF-α, IL-1β, and IL-6) to reduce collagen deposition during pulmonary fibrosis." (PMID 31611754, 2019). "Daily intraperitoneal administration of JSI-124 (1 mg/kg) from day 14 to 28 reduced JAK2 and STAT3 phosphorylation as well as the increased protein levels and cell numbers in BAL, lung mass and protein, and expression of IL-6 and IL-13 secondary to lung fibrosis." (PMID 29409529, 2018). "Interestingly, the previous studies using the mice models of pulmonary fibrosis showed that inhibition of IL-6 signaling attenuates lung fibrosis." (PMID 30258361, 2018). "We present evidence that IL-1-mediated skin and lung fibrosis depends on IL-17 activity and is associated with IL-6 and TNF-α activity, but not with TGF-β." (PMID 30042768, 2018). "Increased TNF-α and IL-6 levels in serum and BALF are associated with lung fibrosis." (PMID 29849496, 2018). "MSCs modulate inflammation and alleviate pulmonary fibrosis caused by bleomycin (mouse model) through reducing lung fibrosis and preventing pulmonary malfunction by lowering secretion of TNF-α, IFN-γ, MCP-1 and IL-6 in lungs." (PMID 28286618, 2017). "The cytokine IL-6 is elevated in mice and humans with pulmonary fibrosis." (PMID 28194150, 2016).
pulmonary fibrosis (continued). "In addition to IL-6 expression, PQ also harbored the ability to induce pulmonary acute inflammation and pulmonary fibrosis." (PMID 28194150, 2016). "Mechanistically, histone acetylation could enhance the transcription of IL-6, which is involved in the progression of PQ-induced pulmonary fibrosis." (PMID 28194150, 2016). "In addition, in vivo neutralization of IL-6 trans-signaling by using recombinant gp130Fc attenuated pulmonary fibrosis phenotype." (PMID 28194150, 2016). "The goal of this study was to determine the impact of IL-6 in paraquat (PQ)-induced pulmonary fibrosis and to explore whether the epigenetic regulations may play a role in transcriptional regulation of IL-6." (PMID 28194150, 2016). "Blockade of IL-6 trans-signaling by GP130Fc attenuated PQ-induced pulmonary fibrosis." (PMID 28194150, 2016). "Interestingly, loss of IL-6 in gp130 mutated mice resulted in protection against bleomycin-induced lung fibrosis, indicating that IL-6 itself is necessary for fibrosis development in this model." (PMID 26867691, 2016). "To evaluate the anti-inflammatory and anti-fibrotic effects of CNP in BLM-induced lung fibrosis, we analyzed mRNA expression changes of pro-inflammatory cytokines (IL-1β and IL-6), pro-fibrotic cytokines and proteins (bFGF, TGF-β, TIMP1, and collagen 1A), and GC-B in the lungs." (PMID 26895702, 2016). "Likewise, BLM-induced lung fibrosis was significantly inhibited by IL-6-neutralizing antibody at 14 dpi." (PMID 26289430, 2015). "Furthermore, neutralization of IL-6, especially at the fibrotic stage of lung injury, significantly inhibits the progression of lung fibrosis." (PMID 26289430, 2015). "Furthermore, blockade of the IL-6 signal during the chronic stages of lung injury shows a beneficial effect on lung fibrosis." (PMID 26289430, 2015). "The present study demonstrated that IL-6 could play a bidirectional role in the pathogenesis of lung fibrosis." (PMID 26289430, 2015). "Moreover, our data also suggested that the protective effect of thalidomide against PQ-induced pulmonary fibrosis was associated with decreased expression levels of inflammatory factors such as TGF-β1, TNF-α and IL-6 in lung tissues after PQ exposure." (PMID 26221080, 2015). "However, it is noteworthy that neutralization of IL-6 at the early inflammatory stage of BLM-induced lung injury accelerated the development of lung fibrosis." (PMID 26289430, 2015). "Our results suggested that IL-6 secreted from EGFR-TKI-treated cancer cells induced lung fibrosis." (PMID 23592411, 2013). "The potential role of IL-6 family molecules directly promoting lung fibrosis was further supported by our observation that genetic ablation of Il6 in gp130757F;Il6−/− mice ameliorated the excessive fibrotic responses induced in bleomycin challenged gp130757F mice." (PMID 22684844, 2012). "In a previous study, CCL2 was hypothesised to contribute to the development of lung fibrosis by reducing IL-6 level." (PMID 22754319, 2012). "Moreover, in vitro studies have demonstrated pro-fibrotic activities of IL-6 on fibroblasts and myofibroblasts, which are considered major effector cells in pulmonary fibrosis." (PMID 21799929, 2011). "Systemic application of a specific APN inhibitor (actinonin) in a silica-induced murine model of lung fibrosis reduced chemokine secretion (e.g., IL-6 and monocyte chemoattractant protein-1) in lung and bronchoalveolar lavage fluid, and resulted in a decreased level of pulmonary fibrosis." (PMID 32201502, 2010). "In addition, various evidences have point out an important role for IL-6 and IL-11 in the pulmonary fibrosis." (PMID 15955252, 2005). "Therefore, IL6 has also been identified as a critical driver of lung fibrosis." (PMID 39781457, 2025).